H4C16 (H4 histone 16)
Description:
Core component of nucleosome. Nucleosomes wrap and compact DNA into chromatin, limiting DNA accessibility to the cellular machineries which require DNA as a template. Histones thereby play a central role in transcription regulation, DNA repair, DNA replication and chromosomal stability. DNA accessibility is regulated via a complex set of post-translational modifications of histones, also called histone code, and nucleosome remodeling.
Synonyms: H4-16; HIST4H4; MGC24116; H4/p
Target class: Other nuclear protein
Gene: Protein-coding gene on chromosome 12 (14,767,999 to 14,771,131, reverse strand). Ensembl gene ENSG00000197837.
Subcellular location: Nucleus; Chromosome
Subcellular location (Human Protein Atlas): Nucleoplasm
Pathways (Reactome):
Gene expression (Transcription): B-WICH complex positively regulates rRNA expression; DNA methylation; ERCC6 (CSB) and EHMT2 (G9a) positively regulate rRNA expression; MLL4 and MLL3 complexes regulate expression of PPARG target genes in adipogenesis and hepatic steatosis; NoRC negatively regulates rRNA expression; PRC2 methylates histones and DNA; RNA Polymerase I Promoter Escape; RNA Polymerase I Promoter Opening; RUNX1 regulates genes involved in megakaryocyte differentiation and platelet function; RUNX1 regulates transcription of genes involved in differentiation of HSCs; Regulation of endogenous retroelements by KRAB-ZFP proteins; Regulation of endogenous retroelements by Piwi-interacting RNAs (piRNAs); Regulation of endogenous retroelements by the Human Silencing Hub (HUSH) complex; SIRT1 negatively regulates rRNA expression; Transcriptional regulation by small RNAs
Chromatin organization: CHD1 and CHD2 subfamily; CHD6, CHD7, CHD8, CHD9 subfamily; ChAHP complex assembly; HATs acetylate histones; HDACs deacetylate histones; HDMs demethylate histones; Interaction of NuRD complexes with transcription factors; NuRD complex assembly; PKMTs methylate histone lysines; RMTs methylate histone arginines
DNA Repair: Cleavage of the damaged purine; Cleavage of the damaged pyrimidine; Nonhomologous End-Joining (NHEJ); Processing of DNA double-strand break ends; Recognition and association of DNA glycosylase with site containing an affected purine; Recognition and association of DNA glycosylase with site containing an affected pyrimidine; Recruitment and ATM-mediated phosphorylation of repair and signaling proteins at DNA double strand breaks
Cell Cycle: Condensation of Prophase Chromosomes; Deposition of new CENPA-containing nucleosomes at the centromere; G2/M DNA damage checkpoint; Inhibition of DNA recombination at telomere; Packaging Of Telomere Ends
Developmental Biology: Activation of anterior HOX genes in hindbrain development during early embryogenesis; Chromatin modifications during the maternal to zygotic transition (MZT); Replacement of protamines by nucleosomes in the male pronucleus
and 20 more pathways
Gene Ontology:
Molecular function: protein binding; RNA binding; structural constituent of chromatin; DNA binding; protein heterodimerization activity
Biological process: negative regulation of megakaryocyte differentiation; nucleosome assembly; chromatin organization; protein localization to CENP-A containing chromatin; telomere organization
Cellular component: CENP-A containing nucleosome; chromosome, telomeric region; extracellular exosome; membrane; nucleoplasm; nucleosome; nucleus; protein-containing complex; extracellular region; chromosome
Genetic constraint (gnomAD): Loss-of-function variants: 6 observed, 6.27 expected, observed/expected ratio (o/e) 0.96, 90% interval 0.52 to 1.74. That is too few expected variants to judge how well the gene tolerates losing a copy. Missense variants: 158 observed, 163.16 expected, observed/expected ratio (o/e) 0.97, 90% interval 0.85 to 1.11. Synonymous variants: 84 observed, 67.87 expected, observed/expected ratio (o/e) 1.24, 90% interval 1.04 to 1.48.
Homologues: Orthologues: chimpanzee H4C6 (100% identical), dog H4C4 (100% identical), macaque H4C13 (100% identical), macaque H4C6 (100% identical), mouse H4c11 (100% identical), mouse H4c2 (100% identical), rabbit H4C1 (100% identical), rat H4c14 (100% identical), tropical clawed frog h4c3 (100% identical), zebrafish hist1h4l (100% identical), zebrafish si:ch211-113a14.6 (100% identical), zebrafish si:dkey-261m9.17 (100% identical), and 1 more. Paralogues in human: H4C1 (100% identical), H4C11 (100% identical), H4C12 (100% identical), H4C13 (100% identical), H4C14 (100% identical), H4C15 (100% identical), H4C2 (100% identical), H4C3 (100% identical), H4C4 (100% identical), H4C5 (100% identical), H4C6 (100% identical), H4C8 (100% identical), and 2 more.